PPARG (peroxisome proliferator activated receptor gamma)
Diseases named in the same sentence as PPARG in open-access papers (continued):
Sharing a sentence is not in itself a finding about the gene and the disease.
gastric cancer (continued). "In gastric cancer cells, phosphatidylinositol transfer upregulates PPARG and CD36." (PMID 36114448, 2022). "Rosiglitazone was found to suppress metastatic potential in gastric cancer, and the enhanced activity of PPARγ resulted in increased direct transcriptional activation of cellular adhesion molecule 3, which inhibits the migration and invasion of gastric cancer cells." (PMID 35954274, 2022). "PPARγ1 upregulation has been detected in malignant tissues such as human prostate and gastric cancer, while PPARγ2 in liposarcoma, suggesting that PPARG dysregulation might be involved in cancer pathogenesis." (PMID 30931956, 2019). "An accumulating evidence suggests that the growth-inhibitory and apoptotic effects of rosiglitazone may often be independent on PPARγ, as documented in non-small cell lung carcinoma and gastric cancer cells." (PMID 26492315, 2015). "PPARγ expression is increased in many types of cancer, including colon, lung, breast, and stomach cancer, suggesting that regulation of PPARγ might affect cancer pathogenesis." (PMID 23516550, 2013). "As H. pylori infection is the main etiologic factor in chronic gastritis and gastric cancer, understanding of the potential roles of PPARγ in H. pylori infection may lead to the development of a therapeutic target." (PMID 22936949, 2012). "Considering that PPARγ activation inhibits the growth of gastric cancer cells, these results suggest that gastric carcinogenesis may have a different genetic background than colorectal carcinogenesis." (PMID 22936949, 2012). "Similarly, PPARγ expression is increased in human gastric cancer tissue, and immunohistochemistry has evidenced its overexpression in gastric mucosal dysplasia and gastric carcinoma compared with chronic gastritis." (PMID 23028383, 2012). "PPARγ suppresses inflammation in H. pylori infection and tumor growth in gastric cancer." (PMID 22936949, 2012). "Therefore, further studies are needed to investigate modulation of PPARγ as an effective therapy for chemoprevention and treatment of inflammation in H. pylori infection and gastric cancer." (PMID 22936949, 2012). "PPARγ is expressed primarily in the nucleus in metastatic gastric cancer." (PMID 22936949, 2012). "PPARγ activation also induces theactivation of the proapoptotic caspase-3 protein in human liver cancer celllines and a reduction in antiapoptotic Bcl-2 and Bcl-XL protein level in humancolon and gastric cancer cell lines, respectively." (PMID 18483618, 2008). "In addition, a Chinese population-based study has revealed that the single-nucleotide variants of PPARγ, PPARGC1A, and PPARGC1B may be related to the susceptibility factors of gastric cancer in an eastern Chinese population." (PMID 38495486, 2024). "In conclusion, PPARγ may become a new therapeutic target for the gastric cancer treatment." (PMID 29483923, 2018). "The inhibitory effect of PPARγ on gastric cancer may be attributed to various mechanisms." (PMID 22936949, 2012). "HSYA treatment increased peroxisome proliferator-activated receptor-γ (PPARγ) and caspase-3 expression in BGC-823 gastric cancer cells, with its inhibitory, apoptotic, and cycle-blocking effects reliant on PPARγ activation." (PMID 40843199, 2025). "Mechanically, AA inhibits the PPARγ pathway to downregulate FABP1 expression, thereby suppressing AA uptake and preventing ferroptosis of gastric cancer cells." (PMID 40694956, 2025). "A study showed that in OCUM-2 MD 3, MKN-74, MCG-803 gastric cancer cell lines, PGD2 and 15-d-PGJ-2 inhibited cancer cell growth, migration, and invasion by activating PPARγ signaling pathway and promoted apoptosis." (PMID 38704736, 2024). "Honokiol activated ER stress and down-regulated peroxisome proliferator-activated receptor-γ (PPARγ) activity resulting in PPARγ and CRT degradation through calpain-II activity in human gastric cancer cell lines and human chondrosarcoma cells." (PMID 31877856, 2019).
gastric cancer (continued). "In gastric cancer, phosphatidylinositol transfer protein cytoplasmic 1 (PITPNC1) upregulates the RNA level of PPARG, and PPARγ then enhances the expression of CD36 and mitochondria CPT1 and thereby elevates FA absorption and promotes FAO and metastasis." (PMID 31410189, 2019). "The seven RNAs upregulated in gastric cancer were CLDN18, EPCAM, REG4, BBC3, OLFM4, PPARG, and CDH17, while the two downregulated genes were IFITM1 and HIF1A." (PMID 22929309, 2012). "For example, it has been described that honokiol induced apoptosis and markedly downregulated the expression of peroxisome proliferator-activated receptor-gamma (PPARγ) and COX-2 in different human gastric cancer cells (AGS, MKN45, N87, and SCM-1) and tumors of xenograft mice." (PMID 39860262, 2025). "Besides, the regulatory role of PGD2 on PPARγ activation and STAT3 phosphorylation was demonstrated in the development of gastric cancer and prostate tumor." (PMID 36725845, 2023). "Conversely, in kidney chromophobe (KICH), kidney renal papillary cell carcinoma (KIRP), stomach cancer (STAD), and liver hepatocellular carcinoma (LIHC), there was a significantly higher PPARG expression level in cancerous tissues compared to paraneoplastic tissues." (PMID 38044948, 2023). "To investigate the potential of the PPARγ partial agonist MEKT-21 as an anti-scirrhous gastric cancer agent, we compared the apoptosis-inducing effects of MEKT-21 and MO-4R, together with the human PPARγ full agonist, troglitazone, on the human scirrhous gastric cancer cell line OCUM-2MD3." (PMID 34502131, 2021). "Moreover, effects on signaling pathways or on PPARG translocation were also observed at higher DHA concentrations, i.e. 20 μM in human gastric cancer cells." (PMID 29122003, 2017). "In addition, ACLY can be downregulated by miR-133b via PPARγ and lncRNA FLJ22763 in gastric cancer." (PMID 32848739, 2020). "PPARγ expression in human gastric cancer cells, however, has not been fully investigated." (PMID 11044367, 2000). "Nine human RNAs were significantly upregulated in EBV-infected compared to EBV negative gastric cancers: FCER2, MS4A1 (CD20), PLUNC, TNFSF9, TRAF1, CXCL11, IFITM1, PPARG, and FCRL3.." (PMID 22929309, 2012). "However, we also noticed that PPARG presented a weak negative correlation with SELENBP1 (RHO = −0.24), which has been shown to increase the chemosensitivity of gastric cancer cells." (PMID 34054937, 2021).
Cerebral ischemia (64 papers, 2012 to 2025). Restriction of arterial blood supply to the brain associated with insufficient oxygenation to support the metabolic requirements of the tissue. "It protects the brain against cerebral ischemia/reperfusion injury by reducing ER stress as evidenced by PPARγ-deficient cells, which had more severe neuron deficits and higher amounts of CHOP, cleaved caspase-12, and BiP." (PMID 38609183, 2024). "In contrast, IL-4 has been associated with protective mechanisms of brain ischemia and can induce anti-inflammatory M2 microglial phenotype expression in primary rat cortical glia cultures and encourage PPARγ-dependent microglial phagocytosis." (PMID 34772945, 2021). "Studies have shown that berberine reduced calcium overload caused by cerebral ischemia by mediating PPARγ." (PMID 33281727, 2020). "PPARγ deficiency increases susceptibility to brain damage after cerebral ischemia, while activation of PPARγ may attenuate ischemic injury through suppressing neuroinflammation." (PMID 23762140, 2013). "Taken together these data suggest that PPARγ activity is important for neuronal survival especially under conditions of cellular stress and this idea is further supported by increased susceptibility to cerebral ischemia in mice with a neuronal deficiency of PPARγ." (PMID 22417924, 2012). "Recent research has highlighted the therapeutic potential of PPARγ agonists in neurodegenerative diseases, including cerebral ischemia/brain injury, AD, and Parkinson's disease (PD)." (PMID 40195204, 2025). "Recombinant human fibroblast growth factor 21 (rhFGF21) has been found to decrease M1-type polarization of microglia after cerebral ischemia, promote M1-to-M2-type polarization transformation, and activate PPARγ in the ischemic penumbra." (PMID 37361996, 2023). "RhFGF21, on the other hand, reduced neuroinflammation after cerebral ischemia by inhibiting NF-κB and upregulating PPARγ, thereby inhibiting M1 polarization and pro-inflammatory cytokine expression in microglia." (PMID 37361996, 2023). "AdipoR2 can lead to the activation of peroxisome proliferator-activated receptor γ (PPARγ), which has been demonstrated in rats with cerebral ischemia to effectively inhibit neuroinflammation by suppressing the release of inflammatory factors." (PMID 38203348, 2023). "In line with our findings, TEL protected against neuroinflammation through PPARγ-mediated inhibition of microglia in PD, cerebral ischemia, and TBI animal models." (PMID 35553009, 2022). "The PPARγ is constitutively expressed in the brain and cerebral ischemia robustly upregulates the PPARγ gene expression in neurons." (PMID 33864097, 2021). "The data substantiates the relevance of cerebral PPARγ for protection of neurons against ischemic damage which at last results in the improved recovery from cerebral ischemia." (PMID 33864097, 2021). "PPARγ was also cited as a possible therapeutic target for the treatment of cerebral ischemia/reperfusion injury." (PMID 33573189, 2021). "Among them, the most interacting genes such as PTGS1 and PPARG are important related genes in the ROS/RNS pathway of E. breviscapus treatment of cerebral ischemia." (PMID 34531475, 2021). "The data of a meta-analysis of experimental studies in rodents subjected to cerebral ischemia suggests that peroxisome proliferator-activated receptor γ (PPARγ) agonists improve the recovery from ischemic stroke." (PMID 33864097, 2021). "It has been well documented that PPARγ agonists show an evident protection against cerebral ischemia in rodents by decreasing the apoptotic rates." (PMID 34944727, 2021). "Cerebral ischemia leads to the upregulation of E3 ligase atrogin-1 and the upregulation of peroxisome proliferator-activated receptor gamma (PPARG)-dependent genes, resulting in myocardial cell atrophy and temporary cardiac dysfunction." (PMID 32231119, 2020).
Cerebral ischemia (continued). "On the other hand, peroxisome proliferator-activated receptor-gamma (PPAR-γ), a nuclear transcription factor has been suggested to exert neuroprotective effect after cerebral ischemia recently." (PMID 32264971, 2020). "PPARγ agonists suppress both processes and give rise to the neuroprotection against cerebral ischemia." (PMID 32774678, 2020). "The administration of pioglitazone (PGZ), a peroxisome proliferator-activated receptor gamma (PPARγ) agonist, before cerebral ischemia induction protected rodents against ischemic brain damage." (PMID 29110250, 2018). "Elsewhere, we demonstrated that treatment with the PPARγ agonist pioglitazone (PGZ) before cerebral ischemia induction reduced brain damage and activated survival-related genes in ovariectomized (OVX) rats." (PMID 29110250, 2018). "Alternatively, targeted inhibition of PPARγ has demonstrated that PPARγ is necessary to facilitate the neuroinflammatory protection observed during cerebral ischemia." (PMID 28656054, 2017). "Compared with the sham-surgery group, 24 hours after cerebral ischemia, PPARγ protein levels were significantly decreased (P < 0.01), while NF-κB 65 protein levels were significantly increased (P < 0.01) in the MCAO injury group." (PMID 28656054, 2017). "This indicated that FNS up-regulated the expression of PPARγ to protect the rats avoid the cerebral ischemia injury." (PMID 26016630, 2015). "On the other hand, it aiso indicated that PPARγ antiinflammatory effect in penumbral region plays an important role in brain ischemia." (PMID 26016630, 2015). "The upregulation of PPARγ is not only related to the inflammatory injury of brain ischemia but also related to the vascular inflammation." (PMID 26844229, 2015). "In this study, using rat cerebral ischemia model, we performed a set of experiments demonstrating that curcumin was a potent PPARγ agonist, which was capable of promoting the survival of neurons, reducing infarct volume, and improving neurobehavioral deficits." (PMID 23762140, 2013). "PPARγ agonists also have been shown to provide neuroprotection in acute central nervous system (CNS) insults like cerebral ischemia, spinal cord injury (SCI) and traumatic brain injury (TBI)." (PMID 23874818, 2013). "In this study, we examined the effects of curcumin on PPARγ expression and activity in a rat model of cerebral ischemia." (PMID 23762140, 2013). "Peroxisome proliferator activated receptor gamma (PPAR gamma) plays a role of a biomarker in cerebral ischemia as CI results in its upregulation and translocation to nucleus from the cytosol." (PMID 23840922, 2013). "Studies have shown that activation of PPARγ contributed to neuroprotection in AD, PD, and cerebral ischemia." (PMID 23762140, 2013). "Third, treatment with PPARγ-selective antagonist abolished the protective effect of low-dose alcohol on transient focal cerebral ischemia-induced brain injury and OGD/reoxygenation-induced apoptosis." (PMID 22848576, 2012). "In addition, many studies also demonstrated the potential role of Rg1 as a PPARγ ligand, which suppresses the cerebral ischemia-reperfusion-induced neuron injury by activating PPARγ." (PMID 39765775, 2024). "Therefore, circ_0000831 can reduce neuroinflammation in cerebral ischemia through the miR-16–5p/ AdipoR2/PPARγ axis." (PMID 38203348, 2023). "Previous studies reported that TEL could inhibit amyloid β (Aβ)-, streptozotocin-, and cerebral ischemia-induced cognitive decline partly through PPARγ action, which agrees with our finding." (PMID 35553009, 2022). "It was observed that the mRNA and protein expression levels of PPARγ were increased in cerebral ischemia, which obtained a maximum level within 24 h, and could still be perceived until 14 days following ischemic injury." (PMID 34944727, 2021). "Similarly, in the rat brain with cerebral ischemia, pioglitazone (a PPARγ agonist) reduced the level of IL-1β but upregulated IL-1Ra." (PMID 31691186, 2020).
Cerebral ischemia (continued). "Ultimately, Rg1 treatment improved neurological function and diminished brain edema, indicating that Rg1 may exert its neuroprotective action on cerebral ischemia/reperfusion injury through the activation of PPARγ signaling." (PMID 28656054, 2017). "In this study, an in vivo and in vitro model of cerebral ischemia was used to answer whether the neuroprotective effects of the traditional Chinese medicine Rg1 could be attributed to PPARγ-mediated regulation of cerebral inflammation and oxidative stress." (PMID 28656054, 2017). "Due to the role that inflammatory and oxidative processes play in the etiology of cerebral ischemia, we hypothesized that Rg1 neuroprotection may occur through recruitment of PPARγ signaling in the ischemic brain." (PMID 28656054, 2017). "Another common point for the mitochondrial dynamics modulation among these PPARγ agonist is the capability of activating PPARγ coactivator 1-α, an important molecule that can counteract excessive oxidative stress and apoptosis in cerebral ischemia." (PMID 27175924, 2016). "Thus, pioglitazone has the potential to reduce neuronal injury after cerebral ischemia through mitochondrial dynamic-related proteins and PPARγ-dependent pathways." (PMID 27175924, 2016). "The cerebral ischemia penumbra tissues were made to detect the expression of PPARγ." (PMID 26016630, 2015). "The neuroprotective effects of FNS have been shown to prolong the therapeutic window in cerebral ischemia/reperfusion, which might be related to the PPARγ mediated-inflammation in penumbral region." (PMID 26016630, 2015). "Owing to the important role of PPARγ on cerebral ischemia, we speculated whether curcumin protected against cerebral ischemic injury through activating PPARγ signaling." (PMID 23762140, 2013). "The results suggested that PPARγ signaling might be involved in the suppression of NF-κB activation in curcumin treated cerebral ischemia rat model." (PMID 23762140, 2013). "So the activation of PPARγ may serve as an adaptive response to protect neurons against the deleterious effects of cerebral ischemia." (PMID 23762140, 2013). "The beneficial effects of curcumin on cerebral ischemia might be due to its activating PPARγ pathway, and ultimately suppressed neuroinflammatory response." (PMID 23762140, 2013). "In recent years, experimental studies in models of cerebral ischemia/reperfusion injury, ischemic stroke, intracerebral hemorrhage, traumatic brain injury and spinal cord injury have revealed a crucial role of PPARγ and its ligands in attenuating neuronal cell death in the injured CNS." (PMID 23874818, 2013). "We have demonstrated previously that the PPARγ agonist, rosiglitazone enhances UCP2 expression in the hippocampal neurons, leading to protection against oxidative stress and neuronal cell death associated with cerebral ischemia." (PMID 22849356, 2012). "It has been reported that the PPARγ agonist rosiglitazone decreases infarct volume and increases GLT-1 expression after cerebral ischemia." (PMID 35401225, 2022). "However, the role of PPARγ’s co-regulators during cerebral ischemia remains largely unknown." (PMID 28526834, 2017). "Our study not only provides the first evidence that PPARγ induced by curcumin may play critical roles in protecting against brain injury through suppression inflammatory response but also highlights the potential of curcumin as a therapeutic agent against cerebral ischemia." (PMID 23762140, 2013). "In this regard, we have demonstrated previously that rosiglitazone, a peroxisome proliferator-activated receptor γ (PPARγ) agonist, enhances UCP2 expression after cerebral ischemia to protect against neuronal cell death in the hippocampus." (PMID 22849356, 2012). "In animal models of cerebral ischemia, PPARγ activation by rosiglitazone also increases CD36 expression in microglia, which contributes to the resolution of inflammation and clearance of infiltrated neutrophils at 48 h following cerebral ischemia." (PMID 37601043, 2023).
Cerebral ischemia (continued). "Furthermore, treatment with the PPARγ agonist 15d-PGJ2 decreased autophagy-related protein expression and LC3 immunoreactivity in mice subjected to cerebral ischemia–reperfusion injury after MCAO." (PMID 36324052, 2023). "However, it might possible that increased expression of PPARγ is not functionally important, as cerebral ischemia reduces the PPARγ-DNA binding, but treatment with PPARγ agonists such as 15-deoxy-PGJ2 or rosiglitazone recovers their functionality." (PMID 34944727, 2021).